BEND5 (BEN domain containing 5)
Description:
Acts as a transcriptional repressor.
Synonyms: C1orf165; FLJ11588
Tractability: PROTAC: UniProt records ubiquitination sites on it; ubiquitination databases record sites on it.
Gene: Protein-coding gene on chromosome 1 (48,727,519 to 48,776,969, reverse strand). Ensembl gene ENSG00000162373.
Subcellular location (Human Protein Atlas): Nuclear speckles; Cytosol
Gene Ontology:
Molecular function: protein binding; DNA binding
Biological process: negative regulation of DNA-templated transcription
Cellular component: Golgi apparatus
Genetic constraint (gnomAD): Loss-of-function variants: 22 observed, 41.63 expected, observed/expected ratio (o/e) 0.53, 90% interval 0.38 to 0.75. The upper end of that interval is the gene's LOEUF score, 0.75, which puts it in group 3 of 6, group 1 being the genes least tolerant of losing a copy. Missense variants: 422 observed, 531.54 expected, observed/expected ratio (o/e) 0.79, 90% interval 0.73 to 0.86. Synonymous variants: 228 observed, 214.94 expected, observed/expected ratio (o/e) 1.06, 90% interval 0.95 to 1.18.
Homologues: Orthologues: chimpanzee BEND5 (100% identical), rabbit BEND5 (99% identical), mouse Bend5 (99% identical), guinea pig BEND5 (98% identical), pig BEND5 (98% identical), dog BEND5 (89% identical), tropical clawed frog bend5 (68% identical), zebrafish bend5 (60% identical), rat Bend5 (50% identical).
Diseases named in the same sentence as BEND5 in open-access papers:
BEND5 is named in the same sentence as 9 diseases in open-access papers, as found by Europe PMC text mining. Sharing a sentence is not in itself a finding about the gene and the disease. The quoted sentences say what the papers report.
colorectal cancer (3 papers, 2017 to 2022). A primary or metastatic malignant neoplasm that affects the colon or rectum. "In colorectal cancer, BEND5 hypermethylation suppresses BEND5 protein expression and promotes cell growth." (PMID 35844785, 2022). "Moreover, the hypermethylation of BEND5 was analyzed to contribute to cell proliferation, and it was proposed as a prognostic marker for colorectal cancer." (PMID 36500178, 2022). "In the current study, BEND5 overexpression could repress colorectal cancer cell proliferation; thus, additional studies should discover drugs that induce BEND5 expression through a Connectivity Map, which uses gene expression signatures to connect small molecules, genes, and disease." (PMID 29371920, 2017).
colon cancer (2 papers, 2017 to 2021). "BEND5 knockdown increased COLO 320DM colon cancer cell growth by 39.75%." (PMID 29371920, 2017). "BEND5 overexpression in DLD-1 colon cancer cells and BEND5 knockdown in COLO 320 DM colon cancer cells indicated that BEND5 could significantly change their expression levels, suggesting that BEND5 may directly or indirectly regulate CCNB1, PCNA and BCL2." (PMID 29371920, 2017).
colorectal tumors (1 paper, 2017). "In contrast to the normal tissues, BEND5 was significantly hypermethylated, with low mRNA expression in the colorectal tumors (Spearman rho = −0.352, P = 0.0005)." (PMID 29371920, 2017). "Taken together, patients with low BEND5 protein expression had a much poorer survival rate than those with high BEND5 protein expression, indicating that low mRNA or protein expression of BEND5 in colorectal tumors is prevalent and is clinically significant for both Asian and Western countries." (PMID 29371920, 2017). "Again, the exon 1 region of BEND5 was hypermethylated in 38 colorectal tumor tissues, but not in the matched normal colorectal tissues." (PMID 29371920, 2017).
Stroke (1 paper, 2022). Sudden impairment of blood flow to a part of the brain due to occlusion or rupture of an artery to the brain. "To further address the potential of NLRP3 inflammasome inhibition as adjunct stroke treatment we used immortalized brain derived endothelial cells (bEnd5) as an in vitro model of the BBB." (PMID 35453512, 2022).
tumor (4 papers, 2011 to 2025). "In this study, through combination of bioinformatics analysis and functional experiments, we identified BEND5 as a vital BC suppressor gene associated with tumor growth and metastasis in vitro and in vivo." (PMID 35844785, 2022). "Multivariate Cox proportional-hazards survival analysis were further adjusted by sex, age, tumor type, location, differentiation, stage showed that hypermethylation of BEND5 genes was significantly and independently associated with overall survival in 105 CRC patients (P = 0.023)." (PMID 29371920, 2017). "Several genes were similarly down-regulated in all T-LGLL, somewhat less markedly in STAT3-mutated cases, e.g. cluster 2 (149 genes, including key receptors like IL23R and KLRB1) and cluster 8 (46 genes, including tumor suppressors like BEND5 and TCEA3)." (PMID 40721648, 2025). "BEND5 mRNA expression was also decreased in patients with larger tumor size, lymph node metastasis as well as distant metastasis." (PMID 35844785, 2022). "As expected, HES1, HEY2, N-cadherin, and Vimentin expression was increased, and E-cadherin expression was decreased in MDA-MB-231 tumor with BEND5 knockdown." (PMID 35844785, 2022). "Taken together, these data suggested that BEND5 knockdown promotes BC tumor growth and metastasis in vivo." (PMID 35844785, 2022). "The data indicated that in 86.7% (117/135) of the CRC patients, hypermethylation of BEND5 was at least 2-fold higher in the tumor tissues than in the matched normal colorectal tissues." (PMID 29371920, 2017). "Analysis of RNA sequencing data from the TCGA showed that BEND5 mRNA expression was markedly significantly reduced in the CRC tumor tissues compared with the matched normal colorectal tissues (P < 0.001)." (PMID 29371920, 2017). "In our case collection, BEND5 mRNA expression in more than two-thirds of our CRC tumor tissues (32/47) was less than 50% of that in the normal control colorectal tissues, as detected by real-time PCR." (PMID 29371920, 2017). "In 68% (32/47) of the paired tissues, BEND5 mRNA expression was 2-fold lower in the tumor tissue than in the normal colorectal tissue." (PMID 29371920, 2017). "By contrast, 34/41 (82.9%) of the tumor samples from the TCGA data set exhibited a significant reduction in the BEND5 transcript level, as demonstrated by RNA sequencing." (PMID 29371920, 2017). "Furthermore, QMSP confirmed BEND5 hypermethylation in the CRC tumor tissues compared with the normal tissues." (PMID 29371920, 2017).
cancer (3 papers, 2011 to 2022). A tumor composed of atypical neoplastic, often pleomorphic cells that invade other tissues. "According to the cell proliferation SRB assay, BEND5 also repressed DLD-1 cancer cell growth by 32.9%, whereas si-BEND5 knockdown increased CRC cell proliferation." (PMID 29371920, 2017). "Since BEN domain could interact with RBPJ in Drosophila according to previous study 17, we speculated that RBPJ may be a potential BEND5 interaction partner in human cancer cells." (PMID 35844785, 2022). "Finally, the cell model assay with transient transfection of BEND5 or si-BEND5 knockdown indicated that BEND5 inhibited cancer cell proliferation." (PMID 29371920, 2017). "Notably, in the G1 phase, BEND5 reduced the proportion of DLD-1 cancer cells by 32.9% but increased cell cycle arrest by only 5%." (PMID 29371920, 2017).
colorectal (1 paper, 2017). "Because the precise role of the DNA methylation of BEND5 in CRC is unclear, we investigated whether the alteration of the BEND5 function is involved in colorectal tumorigenesis." (PMID 29371920, 2017).
infection (1 paper, 2020). The state of being infected such as from the introduction of a foreign agent such as serum, vaccine, antigenic substance or organism. "As VEGF causes paracellular permeability in ECs, we utilized a transwell setup with apical infection of bEnd5 monolayers to assess permeability." (PMID 32529267, 2020).
BEND5 also shares sentences with these, for which no sentence is quoted: breast carcinoma (1 paper).